MIR4710 (microRNA 4710)
Synonyms: hsa-mir-4710; mir-4710
Gene: MicroRNA gene on chromosome 14 (104,677,694 to 104,677,749, reverse strand). Ensembl gene ENSG00000265291.
Homologues: Orthologues: chimpanzee MIR4710 (100% identical).